MIR106AHG (miR-106a-363 cluster host gene)
Gene: Long non-coding RNA gene on chromosome X (134,168,911 to 134,174,129, reverse strand). Ensembl gene ENSG00000283638.
Gene Ontology:
Biological process: miRNA-mediated post-transcriptional gene silencing
Cellular component: RISC complex